SOX2 (SRY-box transcription factor 2)
Diseases named in the same sentence as SOX2 in open-access papers (continued):
Sharing a sentence is not in itself a finding about the gene and the disease.
breast cancer (continued). "In addition, targeting SOX2 in breast cancer cell lines have shown that siRNA-mediated knock-down of SOX2 resulted in cell cycle arrest by down-regulation of Cyclin D1 and this arrest in cell cycle was accompanied by an inhibition of tumor cell proliferation in xenograft models." (PMID 24404135, 2014). "Based on these observations, we tested whether it is possible to use a pluripotency-associated transcriptional reporter, whose activation is driven by the SRR2 enhancer from the Sox2 gene promoter (named S4+ reporter), to isolate cancer stem cells (CSCs) from breast cancer cell lines." (PMID 25414831, 2014). "It has been shown the enhancer is activated upon sphere formation in breast carcinoma cells, suggesting that reactivation of SOX2 expression upon sphere formation may be controlled at the promoter level, in the same way as it is activated in pluripotent stem cells." (PMID 25006803, 2014). "Besides, previous work from our group has shown that the expression of SOX2, a key stemness transcription factor, changes when breast cancer cell lines are maintained in suspension culture, the higher the passage number, the higher the number of SOX2 positive cells in the spheres." (PMID 24124614, 2013). "We also examined whether a rapid elevation of SOX2 could perturb the growth of breast cancer cells." (PMID 22937156, 2012). "However, further studies are needed to deepen our understanding of SOX2 and other embryonic factors during mammary tumorigenesis and larger numbers of prospectively collected samples should be screened before proposing SOX2 as a predictor of lymphonodal status in breast cancer." (PMID 21276239, 2011). "In addition, SOX2 was expressed in 43% of basal cell like breast carcinomas." (PMID 21468047, 2011). "Noteworthy is the link between SOX2 overexpression and tamoxifen resistance in MCF7 breast cancer cells, where MLN4924 treatment was demonstrated to induce MSX2 accumulation through FBXW2 inhibition, ultimately suppressing SOX2 expression." (PMID 40034124, 2025). "Consistently, tumors from breast cancer patients with low butyric acid displayed lower ZFP36 mRNA and higher LRP5/NANOG/SOX2/Ki67 mRNA compared with patients with high butyric acid." (PMID 40038255, 2025). "The expression of SLC6A14 also exhibited a positive correlation with the level of SOX2 in tumors with an odds ratio of 4.40 (p‐value = 0.012) and the hair level of DEHP in breast cancer patients." (PMID 40959920, 2025). "SOX2 can also affect NTRK2 expression, and NTRK2 is essential for tumor migration, potentially by influencing E-cad levels in a manner similar to breast cancer." (PMID 40133476, 2025). "In contrast to the vector control group, the effective knockdown of EBF3 markedly suppressed the upregulated expression of Nanog, OCT4 and SOX2 in MCF-7 and T47D breast cancer cells that exhibited overexpression of SNORA47." (PMID 40264043, 2025). "Silencing SDC1 in breast cancer cells inhibited their proliferation and reduced the protein levels of stem markers CD44, CD133, and SOX2." (PMID 41364407, 2025). "In our current study, we found that in breast cancer cells, overexpression of FOXO3 also downregulated the expression of SOX2." (PMID 39991565, 2025). "The expression of OCT-4 has further been shown in human breast cancer stem-like cells, implicating its involvement in tumorigenesis and self-renewal by activating its downstream target genes, such as NANOG and SOX2." (PMID 41376750, 2025). "In breast cancer, ETV4 and ETV5 are also involved in the maintenance of cancer stem cells and their self‐renewal via the regulation of sox2 or Sonic Hedgehog signalling." (PMID 40275610, 2025). "Here, we showed that genetic inhibition of ITCH increased expression of GATAD2B, SOX2 and MYC, as well as mammosphere formation and CSCs population detected by ALDEFLOUR in multiple breast cancer cell lines." (PMID 40136647, 2025).
breast cancer (continued). "Following chemotherapy for breast cancer, ONECUT2 induces tumor stemness and triggers the expression of stem cell-related genes, including SOX9, SOX2, and NOTCH1, thereby contributing to chemoresistance." (PMID 38997271, 2024). "The transcription factor SOX2 enhances the transcription of PVT1 by combining with the promoter of PVT1, and the upregulated PVT1 promotes the proliferation and invasion of breast cancer cells via EMT." (PMID 38978021, 2024). "In breast cancer, an increase in IL6 secretion from TAMs promoted expression of SOX2, OCT4, and NANOG." (PMID 39287565, 2024). "Simultaneously, SOX2 upregulates CCL1 via activating NF-κB signaling pathway, ultimately recruiting Tregs to the TME, which maintains the CSCs of breast cancer." (PMID 38331879, 2024). "FEZF1-AS1 knockdown decreased the CD44+/CD24- ratio, BCSC cells' capacity to form mammospheres, and the expression of stemness factors (Nanog, OCT4, SOX2), indicating that FEZF1-AS1 silencing has a suppressive effect on the stemness of breast cancer." (PMID 39170516, 2024). "We observed that several genes including PTCH1, ATXN1, DLL4, SOX2 and DACH1 were differentially regulated in tbLCM-treated breast cancer cells as compared to those treated with tnLCM or BM control." (PMID 38581619, 2024). "Breast cancer MDA-MB 231 cells were treated with conditioned medium from SPP1-overexpressed TAM, and tumor stem cell markers (SOX2, CMYC, NANOG, OCT4 gene) and PDL1 genes were detected by RT-qPCR." (PMID 38648200, 2024). "We observed that SOX2 and OCT4 expression was significantly increased in tbLCM-treated breast cancer cells as compared to tnLCM or BM treated cells, while expression of SOX9 and NANOG was not different between treatment conditions." (PMID 38581619, 2024). "Research shows that TAM derived IL-6 upregulates the expression of SOX2, OCT4 and NANOG through STAT3 pathway, and induces CSC enrichment in breast cancer." (PMID 38561775, 2024). "CDDO-Im has been shown to be a potent inhibitor of the epidermal growth factor receptor (EGFR) and STAT3/SRY-Box transcription factor 2 (Sox-2) signaling pathways in tumor-inducing macrophage (TIM) cells, which stimulate breast cancer growth and metastasis." (PMID 39064870, 2024). "Concordantly, OCT4, Nanog, and SOX2 protein expression levels were increased upon co-transfection of tGLI1+GP130 relative to the vector control in both SKBR3 and BT20 breast cancer cells." (PMID 39768178, 2024). "Co-overexpression of tGLI1+GP130 upregulated mRNA expression of OCT4, Nanog, and SOX2 when compared to control and single transfected cells in both SKBR3 and BT20 breast cancer cells." (PMID 39768178, 2024). "For example, According to one study, DNMT1-mediated FOXO3a promoter hypermethylation reduces FOXO3a expression in breast cancer, and FOXO3a decreases breast cancer stem cell characteristics and tumorigenicity through lowering FOXM1/SOX2 signaling." (PMID 38436027, 2024). "Further studies should explore the intricate interactions between SOX2OT, SOX2, and TME in breast cancer subtypes." (PMID 38649821, 2024). "Previous studies suggest that the diverse interactions between SOX2 and SOX2OT plays a crucial role in the progression of breast cancer." (PMID 38649821, 2024). "EpCAM overexpression was shown to promote the expression of stem cell markers (NANOG, SOX2, and OCT4) in breast cancer cell lines." (PMID 39456890, 2024). "TAM-derived IL-6 enhances CSCs phenotype and expression of CSC specific transcription factors including NANOG, SOX2, and OCT3/4, via activating the STAT-3 signaling pathway in breast cancer cells." (PMID 38254782, 2024). "Surprisingly, we found that the Rosa26-RRAS2fl/fl x Sox2-Cre female mice, with ubiquitous expression of RRAS2, that developed breast cancer (BC) were only those that had been pregnant (breeders)." (PMID 38987766, 2024).
breast cancer (continued). "Our data also evidenced that some YAP/TAZ target genes, such as NF2, AXL, SOX2 and BIRC5, were regulated by Bcl-2 specifically in breast carcinoma model." (PMID 38755629, 2024). "SIX1 showed a significant positive correlation with breast cancer stem cell markers such as ALDH1A1, EPCAM, ITGB1, and SOX2." (PMID 38031089, 2023). "To study gains in enhancer features within the SOX2 locus, we initially focused our analyses on luminal A breast cancer, the most common subtype of BRCA to significantly (P = 0.021, Tukey's test) overexpress SOX2." (PMID 37738673, 2023). "Hypoxia induces breast cancer stem cell (BCSC) specification by inducing the expression and/or activity of the pluripotency factors KLF4, NANOG, OCT4, and SOX2." (PMID 37768037, 2023). "Silencing TAZ in tumor cells cultured on stiff supports markedly reduced SOX2 and OCT4 expression, thus indicating that TAZ regulates the stiffness-dependent cancer stemness of breast cancer cells." (PMID 36646707, 2023). "Increasing evidence has illustrated that in breast cancer, CSC resistance to tamoxifen, an ER antagonist, is attributed to the activation of Sox2." (PMID 37853437, 2023). "Specifically, KDM1B, also referred to as lysine-specific demethylase 2 (LSD2), promotes the proliferation of MDA-MB-231 breast cancer cells and induces the expression of pluripotent stem cell markers NANOG and SOX2." (PMID 37761999, 2023). "CypA/CD147 activation induces CSC features in breast cancer cells through the STAT3 and solute carrier family 34 member 2 (SLC34A2)/phosphatidylinositol-3-kinase (PI3K)/AKT/SRY-box transcription factor 2 (SOX2) signaling pathways." (PMID 36902161, 2023). "A heat map generated using data from TCGA (BRCA- breast cancers) showed that OCT4 and MYC were overexpressed in basal-like breast cancers while SOX2 and KLF4 were down regulated in this subtype." (PMID 37515162, 2023). "Our previous study has shown that KDM2A promotes angiogenesis, maintains cancer stemness, and induces drug resistance in breast cancer by regulating jagged-1(JAG-1) and SRY-box transcription factor 2 (SOX-2)." (PMID 37821959, 2023). "Pluripotency markers OCT4, SOX2 with cancer markers BRCA1, BRCA2, ER, PR and HER2 in breast cancer iPSCs; Tal2, EGF, ILF3, UBI2I, BRCA1 and BRCA2 in ovarian cancer iPSCs were analyzed." (PMID 37479967, 2023). "Our analysis revealed significantly higher CSC-related stemness genes (OCT4, SOX2, NANOG) (p < 0.0001) and ALDH1A1 (p < 0.0001) in TNBC (GSE30682), in contrast to ER+ luminal breast cancer (GSE5460)." (PMID 38038865, 2023). "Using a Sox2 reporter (i.e., SRR2), our group has previously demonstrated the acquisition of stemness in breast cancer and lymphoma cells exposed to oxidative stress." (PMID 38203669, 2023). "ALG3 can increase the radioresistance and tumor stemness of breast cancer cells and can upregulate several key CSC-like markers (Nanog, OCT4, and SOX2) by promoting the glycosylation of TGF-beta receptor II." (PMID 35899200, 2022). "In a previous study, researchers engineered three ATFs that bind to the proximal SOX2 promoter and one ATF that targets SOX2 regulatory region I (SRR1), one of which inhibits the expression of SOX2 in breast cancer cells by as much as 94%." (PMID 35267473, 2022). "Compound 7 inhibited HER2-positive BC via reducing SOX2-driven breast cancer stem cells." (PMID 36188536, 2022). "In 2015, Kim and co-workers reported that 1 exhibited anticancer activity against breast cancer stem-like cells by reducing the expression of CD44, Oct4, Notch2, β-catenin and Sox2 proteins." (PMID 35209235, 2022). "Six target genes (FGFR2, RET, ERBB4, SOX2, FN1, and MMP16) were analyzed across breast cancer studies using the cBioPortal to assess genomic alterations." (PMID 36601474, 2022). "SOX2 can inactivate FOXO1 in embryonic stem cells, while FOXO1 can inhibit SOX2 transcription in breast cancer cells." (PMID 36293387, 2022).
breast cancer (continued). "As two key transcription factors involved in the tumor progression and differentiation, OCT4 and SOX2 enhance tumor cell stemness and serve as CSC markers in various cancer types, including breast cancer." (PMID 35402219, 2022). "We performed qRT-PCR for the major stemness-related transcription factors, such as NANOG, SOX2, OCT4 and BMI1, as well as the marker CD44, a panel that predicts a transcriptional shift to a stem-like state in breast cancer cells." (PMID 35195687, 2022). "Overexpression of SOX‐2 increased the spheroid‐forming ability and self‐renewal in CSCs,39 suggesting that SOX‐2 is a key molecule regulating the formation of CSCs in early breast cancer." (PMID 34914196, 2022). "Iadademstat targets Sox2-driven breast cancer stem cells and can be a candidate for epigenetic therapies in luminal-B and HER2 positive breast cancer." (PMID 36011043, 2022). "The activation of this signaling pathway promotes the expression of the stem transcription factors SOX2 and NANOG, as well as CD44, which is one of the reported stem markers in breast cancer." (PMID 35954194, 2022). "SOX2 has a primary role in promoting tumor development in many malignancies other than GBM, including medulloblastoma and lung, prostate, and breast cancers." (PMID 35921410, 2022). "In breast cancer, Tamoxifen-resistant MCF7 cells express higher levels of SOX2 than parental MCF7 cells." (PMID 36566021, 2022). "Treating breast cancer cell lines with TGFβ increases the expression levels of BCSC markers, including Nanog, Pou5f1, and Sox2." (PMID 35805056, 2022). "This pathway is activated in multiple types of human cancers, including ovarian cancer, brain cancer, breast cancer, and metastatic renal cell carcinoma, and maintains the pluripotency of stem cells through the PI3K/Akt/Sox2 axis." (PMID 36013373, 2022). "In total, 160 breast cancer patients were enrolled following the immunofluorescence assay to detect tumor OCT4 and SOX2 expressions." (PMID 35402219, 2022). "When GPNMB-positive cells form spheres in breast cancer, the expression levels of CSC markers such as SOX2, NANOG, OCT4, CD44, CD133, and FOXO3 are elevated." (PMID 36061142, 2022). "For example, LSINCT5 and Zfas one can promote the proliferation of breast cancer, HOTAIR suppresses invasion and migration of breast cancer, SOX2OT induces SOX2 expression in breast cancer, and SRA is the expression activator of breast cancer." (PMID 36744179, 2022). "TRIB3 is positively associated with breast cancer stemness and progression by inhibiting FOXO1 degradation and increasing SOX2 transcription and the cellular stress-activated TRB3/USP9x-dependent Notch pathway in breast cancer." (PMID 36463181, 2022). "In MCF-7 breast cancer cells stimulated with PA, Nobiletin mimics the effects of CD36 knock-down, decreasing tumorsphere formation, the expression of stemness markers (SOX2, OCT4 and NANOG), STAT3 phosphorylation, and NF-kB activation." (PMID 36568966, 2022). "The only member of DEAD-box RNA helicases family which has exactly effects on breast cancer stem cells is DDX17, who can enhance stem cell-like activities by combining with SOX2 or mechanism of promoting stem-like properties under hypoxia." (PMID 34362383, 2021). "For example, in colorectal carcinoma, SOX2 promotes cancer through methylation catalyzed by METTL3, while in breast cancer, BNIP3 promotes the cancer through demethylation catalyzed by FTO." (PMID 34489709, 2021). "Intriguingly, in luminal breast cancers, IFN-β promotes stemness via induction of SOX2 and STAT3 activity." (PMID 35582030, 2021). "Our data indicate that decreased expression of SOX2 and AGR2 with low serum level of serum AGR2 clearly related to breast cancer patients who respond and had benefit from tamoxifen-based therapy." (PMID 34567804, 2021).
breast cancer (continued). "Expected staining patterns were demonstrated in control human tissues: seminoma for OCT4, normal skin for SOX2, seminoma for NANOG, breast cancer for KLF4 and normal prostatic tissue for c-MYC." (PMID 34685477, 2021). "LINC00617 is elevated in breast cancer samples and functions as an important regulator of EMT, enhancing the progression and metastasis via upregulating Sox2." (PMID 34360879, 2021). "miR-302b maintain SOX2 and c-MYC to produce cytokine-induced cancer stem cell-like properties in breast cancer cell co-cultured with immature adipocyte; whilst miR-302b in breast cancer targets RUNX2, an activator of PI3K/AKT signaling." (PMID 33482868, 2021). "Although SCIRT is upregulated during the tumorigenesis of breast cancer, it suppresses the cancer cell self-renewal mechanism by counteracting EZH2 and SOX2 to suppress cancer progression." (PMID 34742341, 2021). "HIF-1α can induce pluripotent stem cell inducers, such as OCT4, NANOG, SOX2, KLF4, c-MYC, and microRNA-302, in 11 cancer cell lines (derived from prostate, brain, kidney, cervix, lung, colon, liver, and breast cancers)." (PMID 34064635, 2021). "In our breast cancer cell model, the expression of Cx46GFP increased mRNA levels of OCT4 and Sox2; however, the Nanog mRNA levels were unchanged." (PMID 34830485, 2021). "In order to determine the mechanism governing the regulation of CSC by piR-823 in breast cancer cells, stem cell-regulating factors including OCT4, SOX2, KLF4, NANOG, and h-TERT were examined in MCF-7 cells after knockdown or overexpression of piR-823." (PMID 33791297, 2021). "SCIRT plays critical roles in breast cancer, where it counteracts EZH2 and SOX2 to suppresses cancer cell self-renewal mechanism, thereby inhibiting cancer progression." (PMID 34742341, 2021). "miRNA-101 was found to target different pathways that promote breast cancer cell apoptosis by inhibiting the expression of Jak2, EYA1 and SOX2 acting as a potential therapeutic target in breast cancer." (PMID 34200314, 2021). "To further elucidate DDX27 as a breast cancer stem cell biotarget, we transfected over-expression and negative control plasmid into MCF-7 and T47D cells and found that SOX2 and OCT4 were up-regulated in DDX27 overexpressed cells on protein levels." (PMID 34362383, 2021). "Correspondingly, ectopic CBY1 significantly decreased SOX2, Nanog, and CD44, the representative breast cancer stemness marker expressions both in mRNA and protein levels, implying that CBY1 has the ability to inhibit the stemness of BCSCs." (PMID 33934099, 2021). "In agreement with our observations, forced overexpression of HSF-1 increased mammosphere-forming ability as well as CD44, Sox2 and ALDH1 expression, and conferred drug resistance in breast cancer, while HSF-1 knockdown attenuated these phenomena." (PMID 34775489, 2021). "Positive controls showed expected staining for OCT4 and NANOG in seminoma, SOX2 in skin, KLF4 in breast carcinoma, and c-MYC in normal colon." (PMID 33816543, 2021). "In our study, we showed that tangeretin had antiproliferative effects on breast cancer cells and reduced BCSC proliferation or prevalence through a decrease in Sox2 expression by inhibiting Stat3 signaling." (PMID 32503228, 2020). "We found that the combination of low FOXO3a expression and high FOXM1, SOX2, and DNMT1 expression was a strong predictor of shorter survival in breast cancer patients." (PMID 31296961, 2020). "We found that, in general, adjacent normal tissues exhibited relatively high FOXO3a expression and very low expression of FOXM1, SOX2, and DNMT1; in contrast, breast cancer tissues had low FOXO3a, but high FOXM1, SOX2, and DNMT1 expression." (PMID 31296961, 2020). "Here we designate the MLN4924 to be a man with slingshot, who ultimately targets the cicada (SOX2) via oriole (FBXW2) and mantis (MSX2), to regulate stem cell property and sensitize breast cancer cells to tamoxifen." (PMID 31748974, 2020).